KTN1-AS1 (KTN1 antisense RNA 1)
Synonyms: C14orf33; MYCLo-3
Gene: Long non-coding RNA gene on chromosome 14 (55,496,786 to 55,581,068, reverse strand). Ensembl gene ENSG00000186615.
Diseases named in the same sentence as KTN1-AS1 in open-access papers:
KTN1-AS1 is named in the same sentence as 3 diseases in open-access papers, as found by Europe PMC text mining. Sharing a sentence is not in itself a finding about the gene and the disease. The quoted sentences say what the papers report.
tumor (1 paper, 2023). "In this study, we want to clarify the expression, biological function, and molecular mechanism of lncRNA KTN1 antisense RNA 1 (KTN1-AS1) in GBM tumor progression." (PMID 36762036, 2023).
KTN1-AS1 also shares sentences with these, for which no sentence is quoted: cancer (1 paper); glioma (1).